CX3CL1 (C-X3-C motif chemokine ligand 1)
Diseases named in the same sentence as CX3CL1 in open-access papers (continued):
Sharing a sentence is not in itself a finding about the gene and the disease.
ischemia (7 papers, 2010 to 2023). A hypoperfusion of the BLOOD through an organ or tissue caused by a PATHOLOGIC CONSTRICTION or obstruction of its BLOOD VESSELS, or an absence of BLOOD CIRCULATION. "Here, we investigated the involvement of CX3CL1 in microglia phenotype and metabolic switch toward oxidative metabolism and the underlying neuroprotective effect toward ischemia injury." (PMID 31607865, 2019). "Here, we investigated the involvement of CX3CL1 in the modulation of microglia phenotype and the underlying neuroprotective effect on ischemia injury." (PMID 31607865, 2019). "For instance, experimental autoimmune encephalomyelitis (EAE) and ischemia are associated with an induction of CX3CL1 and an accumulation of CX3CR1-expressing cells." (PMID 21167054, 2010). "However, administration of exogenous CX3CL1, to CX3CL1-deficient mice, post ischemia, resulted in neurotoxicity and increased infarct size." (PMID 27549131, 2016). "Neuronal autophagy was prominently activated bycerebral ischemia, whereas CX3CL1 expression in autophagic neurons wasconversely down-regulated to exacerbate microglial inflammation." (PMID 37908770, 2023). "The use of exogenous CX3CL1 in a MCAO mouse model reduced the local ischemia-induced cerebral infarct size, neurological deficits, and caspase-3 activation." (PMID 34276530, 2021). "The CX3CL1/CX3CR1 signaling axis promotes microglial phagocytic function in the early phase after ischemia." (PMID 34276530, 2021). "Since CX3CL1 is neuroprotective in ischemia and it is known that neuro-inflammation plays a role in brain damage following ischemic insult, we wanted to verify the hypothesis that the neuroprotective effect of CX3CL1 was due to its ability to modulate the phenotype of microglia." (PMID 31607865, 2019).
myocardial infarction (7 papers, 2019 to 2025). Gross necrosis of the myocardium, as a result of interruption of the blood supply to the area, as in coronary thrombosis. "CX3CL1 is a cytokine that is upregulated in the myocardium of patients with chronic HF and the cardiomyocytes of mice with myocardial infarction (MI)." (PMID 37019881, 2023). "Our in vivo data indicated a ADAM10/CX3CL1 axis to control neutrophil infiltration upon myocardial infarction." (PMID 36496449, 2022). "We next assessed cardiac expression of CX3CL1 and IL-1β at 3, 14 and 28 days post myocardial infarction using immunoblot analysis." (PMID 36496449, 2022). "In contrast, it was shown that CX3CL1 neutralization in a murine myocardial infarction model resulted in improved survival." (PMID 31704966, 2019).
neuroblastoma (7 papers, 2012 to 2024). Neuroblastoma (NB) is the most common solid, extracranial childhood tumor. "Both gain-of-function and loss-of-function studies showed that HIF-1α affected the chemotactic migration of PDAC cells toward supernatants of activated neuroblastoma (conditioned supernatants) and CX3CL1." (PMID 22952674, 2012). "In other studies, delivery of the CX3CL1 gene into NB cell lines induces an effective antineuroblastoma immune response mediated by NK cells and T lymphocytes." (PMID 24799766, 2014). "In addition, some studies have confirmed that CX3CL1 significantly enhances NK cell cytotoxicity, IFN‐γ expression and secretion to inhibit neuroblastoma proliferation and metastasis." (PMID 33191645, 2021). "Similar results were observed for AktSer473phosphorylation at time points 10, 20 and 40 min upon chemokine stimulation.A similar time course of kinase phosphorylation by CX3CL1 was described formonocytic cells, CX3CR1-transfected HEK293T cells, neuroblastoma and osteoarthritisfibroblasts." (PMID 28739588, 2017).
neuropathy (7 papers, 2013 to 2025). A disorder affecting the nervous system that manifests with pain, tingling, numbness, and/or muscle weakness. "As a result, novel therapeutic interventions aimed at blocking CX3CR1 may prove to be beneficial in attenuating sensory abnormalities associated with neuropathies associated with CX3CL1 induction." (PMID 24175290, 2013). "Other studies have confirmed the role of chemokine CXCL12 and chemokine CX3CL1 signaling in oxaliplatin-induced neuropathy." (PMID 37834455, 2023). "Levels of CX3CL1 were increased in the DRG after nerve injury, whereas blocking CX3CL1 inhibited the recruitment of macrophages to the DRG and attenuated allodynia in paclitaxel-induced neuropathy." (PMID 33535595, 2021).
psoriasis (7 papers, 2009 to 2025). An autoimmune condition characterized by red, well-delineated plaques with silvery scales that are usually on the extensor surfaces and scalp. "Recently another chemokine CX3CL1 called Fractalkine (in humans) or neurotactin (in mice) has been identified in Psoriasis." (PMID 20049260, 2009). "Both, CX3CL1- as well as C5a are expressed in psoriasis plaques." (PMID 31191513, 2019). "The involvement of the CX3CL1-CX3CR1 axis in T cell homing to the CX3CL1-producing cells in skin as well as their correlation with disease severity is supported by studies investigating normal and inflamed tissues and/or blood from human and mouse models of AD and psoriasis." (PMID 36675078, 2023). "The migration of slanMo from the peripheral blood into psoriasis skin lesions may be facilitated by the local expression of the anaphylatoxin C5a, fractalkine (CX3CL1), and CXCL12 for which the respective receptors are expressed by slanMo (C5aR, CX3CR1, and CXCR4)." (PMID 31191513, 2019).
retinal degeneration (7 papers, 2010 to 2025). Degeneration of the retina. "We aimed to investigate fractalkine (CX3CL1) protein expression in wild type (wt) retina and its alterations during retinal degeneration in mouse model (rd10) of retinitis pigmentosa." (PMID 25191897, 2014). "Certain chemokines, such as CCL2 and CX3CL1, appear to be crucial in subretinal microglia and macrophage accumulation observed in AMD, and participate in the development of retinal degeneration as well as in choroidal neovascularization." (PMID 21126357, 2010). "In fact, in the RP-mimicking retina degeneration induced in rats by N-methyl-N-nitrosourea (MNU), the Mϋller glia enhanced the secretion of Cx3cl1 cytokine, which induced an increase in Cx3cl1 levels in microglia and triggered their migration to the outer retina." (PMID 34834350, 2021).
age-related macular degeneration (6 papers, 2010 to 2019). Age-related loss of vision in the central portion of the retina (macula), secondary to retinal degeneration. "Defining the role of Ccl2-Ccr2 and Cx3cl1-Cx3cr1 signalling for retinal pathology is of particular interest because of its potential role in age-related macular degeneration (AMD)." (PMID 22545116, 2012). "Apart from AD, CX3CL1/CX3CR1 is also involved in other neuroinflammation disorders, including Parkinson's Disease (PD), multiple sclerosis (MS), tauopathies, and age-related macular degeneration (ARMD)." (PMID 27429982, 2016).
brain injuries (6 papers, 2013 to 2023). "However, CX3CL1-induced neuroprotection is ineffective in CX3CR1- or CX3CL1-deficient mice, confirming the duality and complexity of microglia and inflammation in brain injuries." (PMID 34831273, 2021). "CCL2, CXCL1 and CX3CL1 all stimulate the proliferation and migrationof vascular endothelial cells, which indicates that these chemokines have similar actions onneovascularization after brain injuries." (PMID 23627909, 2013). "CX3CL1/CX3CR1 is an important pathway involved in the crosstalk between neurons and microglia, which functions differentially in acute and chronic brain injuries." (PMID 37234914, 2023).
chronic kidney disease (6 papers, 2021 to 2025). Impairment of the renal function secondary to chronic kidney damage persisting for three or more months. "Systemic activation of CX3CL1/CX3CR1 contributes to chronic kidney disease-associated cardiovascular disease." (PMID 38299151, 2023). "As a uremic toxin, indoxyl sulfate is highly expressed in the serum of end-stage renal disease (ESRD) patients and has been reported to cause vascular damage through the TNF-α/CX3CL1 axis." (PMID 39996729, 2025). "In this article we have highlighted a wealth of research from the past two decades that indicates a predominantly pathogenic role for the CX3CL1- CX3CR1 axis during both acute and chronic renal diseases." (PMID 34163473, 2021). "Taken together, these data suggest the angiotensin pathway as a mechanism that elevates CX3CL1 in chronic kidney disease." (PMID 34009468, 2021). "The aortic CX3CL1/CX3CR1 axis is upregulated in chronic kidney disease in mice." (PMID 38299151, 2023). "Plasma CX3CL1 was elevated in chronic kidney disease (CKD) patients and negatively correlated with estimated glomerular filtration rate (eGFR), suggesting a relationship between CKD and the CX3CL1/CX3CR1 axis." (PMID 40508161, 2025). "Since the discovery of the chemokine fractalkine (CX3CL1) and its receptor, CX3CR1 over twenty years ago, a wealth of evidence has emerged linking CX3CL1-CX3CR1 signalling to renal pathologies in both acute and chronic kidney diseases (CKD)." (PMID 34163473, 2021).
chronic obstructive pulmonary disease (6 papers, 2017 to 2025). A chronic and progressive lung disorder characterized by the loss of elasticity of the bronchial tree and the air sacs, destruction of the air sacs wall, thickening of the bronchial wall, and mucous accumulation in the bronchial tree. "Notably, studies have revealed a significant increase in CCL18 and CX3CL1 levels in patients with conditions such as chronic obstructive pulmonary disease (COPD) and chronic cough with phlegm (CCP) when compared to healthy individuals." (PMID 37944262, 2023).
experimental autoimmune encephalomyelitis (6 papers, 2010 to 2019). An autoimmune demyelinating disease of the central nervous system that is produced experimentally in animals by the injection of homogenized brain or spinal cord in Freund's adjuvant. "In a myelin oligodendrocyte glycoprotein (MOG)-induced experimental autoimmune encephalomyelitis (EAE) rat model of MS, neuronal CX3CL1 was reported unchanged and remained at control levels." (PMID 27549131, 2016). "An experimental autoimmune encephalomyelitis (EAE) model of MS was utilized to assess time dependent gene and protein expression changes of CX3CL1 and CX3CR1." (PMID 24175290, 2013).
gastric cancer (6 papers, 2020 to 2025). A primary or metastatic malignant neoplasm involving the stomach. "In colon and gastric cancer, high CX3CL1 expression is associated with a favorable prognosis, primarily through its recruitment of CD8+ T cells and natural killer (NK) cells, which promote antitumor immunity." (PMID 40051011, 2025). "The significance of CX3CL1 mutations in cancer is yet poorly understood, but different mutations in this gene have been reported in other tumor types, predominantly in gastric cancer (COSMIC) and HCCs (TCGA)." (PMID 32432034, 2020). "In gastric cancer, tumor-derived lactate engages GPR81, initiating the nuclear translocation of phosphorylated p65 and activating C-X3-C motif chemokine ligand 1 (CX3CL1) transcription." (PMID 41152975, 2025).
glomerulonephritis (6 papers, 2014 to 2024). A renal disorder characterized by damage in the glomeruli. "Human expression data and experimental models consistently support a pathophysiologic role of CX3CL1/CX3CR1 in inflammatory processes in the renal cortex such as glomerulonephritis and transplant rejection." (PMID 34009468, 2021). "Upregulation of CX3CL1, expressed preferentially on the apical membrane of renal tubular epithelial cells, has been reported in glomerulonephritis where CX3CL1 acts as a chemoattractant and adhesion molecule." (PMID 24799766, 2014). "An important role for the CX3CL1/CX3CR1 axis has also been demonstrated in renal diseases such as glomerulonephritis, tubulointerstitial nephritis, pyelonephritis, and renal allograft rejection." (PMID 24799766, 2014). "Additionally, CX3CL1 acts as a chemoattractant and adhesion molecule in glomerulonephritis." (PMID 38299151, 2023). "More and more data confirm that CX3CL1/CX3CRI is involved in various immune inflammatory diseases, such as glomerulonephritis, rheumatoid arthritis, and systemic lupus erythematosus." (PMID 38937701, 2024). "Expression of both CX3CL1 and CX3CR1 were increased after the induction of anti-GBM glomerulonephritis." (PMID 34163473, 2021). "CX3CL1 expression recruits CX3CR1+ cells and prolong glomerulonephritis." (PMID 38299151, 2023). "Indeed the apical CX3CL1, firmly anchored to the membrane, facilitates recruitment and retention of the majority of CX3CR1+ leukocytes that infiltrate the kidney during glomerulonephritis or other nephropathies." (PMID 24799766, 2014).
liver cancer (6 papers, 2017 to 2025). An epithelial or non-epithelial malignant neoplasm that arises from the liver. "Another study showed that patients with high expression of CX3CL1 and CX3CL1 receptors would have a significantly better prognosis in liver cancer." (PMID 34671562, 2021). "The high expression of FARSB may constitute an immunosuppressive microenvironment by affecting the expression levels of relevant chemokines, CCL26 and CX3CL1, and helping the infiltration of Th2 cells, resulting in a poor prognosis for liver cancer patients." (PMID 37074800, 2023). "Therefore, the high expression of FARSB may constitute an immunosuppressive microenvironment by affecting the expression levels of relevant chemokines, CCL26 and CX3CL1, and helping the infiltration of Th2 cells, resulting in a poor prognosis for liver cancer patients." (PMID 37074800, 2023).
non-small cell lung carcinoma (6 papers, 2021 to 2025). A group of at least three distinct histological types of lung cancer, including non-small cell squamous cell carcinoma, adenocarcinoma, and large cell carcinoma. "However, in non-small cell lung carcinoma, high expression of CX3CL1 was associated with a worse prognosis after immunotherapy." (PMID 36397015, 2022). "In non-small cell lung cancer, plasma CX3CL1 levels increased in non-responders to anti-PD-1 therapy." (PMID 37771579, 2023).
peripheral nerve injury (6 papers, 2015 to 2023). Injury to a peripheral nerve. "Consistent with that possibility, the chemokines CCL2, CCL3, and CX3CL1 are all highly expressed after peripheral nerve injury with the corresponding chemokine receptors, CCR2, CCR5, and CX3CR1 expressed by NK cells." (PMID 30712871, 2019). "Moreover, after peripheral nerve injury, membrane-bound CX3CL1 is reduced in the cell bodies of sensory neurons, suggesting their release and action in the sNAMs." (PMID 37254842, 2023).
preeclampsia (6 papers, 2009 to 2025). Preeclampsia is a hypertensive disorder of pregnancy that is characterized by new-onset hypertension with proteinuria presenting after 20 weeks of gestation, and depending on mild or severe forms may initially present with severe headache, visual disturbances, and hyperreflexia. "Elevated placental CX3CL1 expression is associated with several pregnancy complications including chorioamnionitis, gestational diabetes, and preeclampsia." (PMID 41463301, 2025). "The significant underdevelopment of placental vascular network in preeclampsia is associated with the change in the CX3CL1/CX3CR1 system, especially in FGR complicated pregnancies." (PMID 33496844, 2021). "Furthermore, a growing body of evidence suggests that a number of pregnancy pathologies, including chorioamnionitis, diabetic pregnancy, and severe early-onset preeclampsia (PE), are associated with increased placental CX3CL1 expression." (PMID 30717334, 2019). "CX3CL1 release increases during the third trimester primarily through metalloproteinase activity, which is also elevated in preeclampsia." (PMID 41463301, 2025). "The release of CX3CL1 is increased in the third trimester mainly thanks to the activity of metalloproteases and their activity is also increased in cases of preeclampsia." (PMID 33496844, 2021). "Summing up, CX3CL1 should be discussed as another player involved in the pathogenesis of preeclampsia, especially in pregnancies complicated by fetal growth restriction." (PMID 33496844, 2021). "The separate measurement of placental-derived CX3CL1 would give more precise look insight the behaviour of CX3CL1 while preeclampsia development, however it cannot be performed before delivery is finished." (PMID 33496844, 2021). "TNF-α, which is upregulated in preeclampsia, is the strongest stimulator of CX3CL1 synthesis in placenta." (PMID 33496844, 2021). "It seems that in the case of preeclampsia, we have a kind of insensitivity of placental vessels for the angiogenetic action of CX3CL1/CX3CR1, which is observed elsewhere." (PMID 33496844, 2021). "It has been found that the placental secretion of CX3CL1 is significantly increased in cases of severe preeclampsia." (PMID 33496844, 2021). "In this study, a link between CX3CL1 and the development of placental vasculature in preeclampsia was examined." (PMID 33496844, 2021). "Another important issue is the observation of the CX3CL1 variability along with the duration of pregnancy, also if the changes in CX3CL1 can predict the beginning of preeclampsia in any manner." (PMID 33496844, 2021). "Placental CX3CL1 is induced by inflammatory cytokines and is upregulated in severe early-onset preeclampsia." (PMID 30717334, 2019). "In contrast, we found a trend toward increased CX3CL1 levels in preeclampsia patients, especially in early-onset- preeclampsia as compared to its level in later-onset- preeclampsia." (PMID 19587779, 2009). "Additionally, other data show that early-onset preeclampsia is characterized by elevated CX3CL1 expression in the placenta." (PMID 33496844, 2021). "Therefore, placental expression of CX3CL1/CX3CR1 in preeclampsia can be a part of a developed inflammatory reaction." (PMID 33496844, 2021). "A multidimensional correlation analysis showed the significant impact of preeclampsia for correlation between V/EVTI and CX3CL1 serum level (r2 = 0.59, p = 0.005)." (PMID 33496844, 2021). "There was a moderate negative correlation between birth weight, V/EVTI and CX3CL1 serum level and CX3CR1 placental expression in the group of pregnancies complicated with preeclampsia." (PMID 33496844, 2021).
primary biliary cholangitis (6 papers, 2020 to 2025). Primary biliary cholangitis (PBC) is a chronic and slowly progressive cholestatic liver disease of autoimmune etiology characterized by injury of the intrahepatic bile ducts that may eventually lead to liver failure. "For example, E6011 is a novel humanized anti-CX3CL1 monoclonal antibody being developed as a therapeutic target for Crohn’s disease, RA, and primary biliary cholangitis." (PMID 34017692, 2021). "The only known CX3C chemokine, fractalkine (CX3CL-1), is overexpressed in senescent biliary epithelial cells and it is thought to exacerbate ductal inflammation in primary biliary cholangitis." (PMID 32185730, 2020). "For example, CX3CL1 (one chemokine) is secreted in some chronic liver diseases, such as alcoholic liver disease (ALD), autoimmune hepatitis (AIH) and primary biliary cirrhosis (PBC)." (PMID 35185900, 2022). "Moreover, CX3CL1/CX3CR1 signaling triggers a rapid mobilization and accumulation of immune cells to the sites of injury and is involved in several inflammatory diseases, such as primary biliary cholangitis (PBC)." (PMID 32784743, 2020).
vasculitis (6 papers, 2014 to 2024). "Moreover, serum levels of CX3CL1 were found to be high in RA patients with rheumatoid vasculitis, and to correlate with vasculitis disease severity and levels of inflammatory markers." (PMID 36294363, 2022). "In accordance with these previous findings, high levels of CX3CL1 in patients with severe RSV infection in this study might be correlated with vasculitis." (PMID 36294363, 2022).